POMP (proteasome maturation protein)
Description:
Molecular chaperone essential for the assembly of standard proteasomes and immunoproteasomes. Degraded after completion of proteasome maturation. Mediates the association of 20S preproteasome with the endoplasmic reticulum.
Synonyms: C13orf12; UMP1; HSPC014; PNAS-110; PRAAS2
Tractability: PROTAC: UniProt records ubiquitination sites on it; ubiquitination databases record sites on it.
Gene: Protein-coding gene on chromosome 13 (28,659,065 to 28,678,959, forward strand). Ensembl gene ENSG00000132963.
Subcellular location: Cytoplasm, cytosol; Nucleus; Microsome membrane
Subcellular location (Human Protein Atlas): Nuclear speckles
Pathways (Reactome):
Metabolism of proteins: Proteasome assembly
Gene Ontology:
Molecular function: protein binding
Biological process: proteasome assembly
Cellular component: nuclear speck; cytoplasm; cytosol; nucleus
Genetic constraint (gnomAD): Loss-of-function variants: 7 observed, 11.04 expected, observed/expected ratio (o/e) 0.63, 90% interval 0.36 to 1.19. The upper end of that interval is the gene's LOEUF score, 1.19, which puts it in group 5 of 6, group 1 being the genes least tolerant of losing a copy. Missense variants: 99 observed, 124.7 expected, observed/expected ratio (o/e) 0.79, 90% interval 0.67 to 0.94. Synonymous variants: 40 observed, 45.57 expected, observed/expected ratio (o/e) 0.88, 90% interval 0.68 to 1.14.
Homologues: Orthologues: chimpanzee POMP (100% identical), macaque POMP (99% identical), rat Pomp (96% identical), guinea pig POMP (94% identical), mouse Pomp (94% identical), pig POMP (94% identical), rabbit POMP (83% identical), zebrafish pomp (76% identical), tropical clawed frog pomp (74% identical), Drosophila melanogaster Pomp (40% identical).
Diseases named in the same sentence as POMP in open-access papers:
POMP is named in the same sentence as 24 diseases in open-access papers, as found by Europe PMC text mining. Sharing a sentence is not in itself a finding about the gene and the disease. The quoted sentences say what the papers report.
KLICK syndrome (4 papers, 2012 to 2020). "This review summarized the pathogenesis and clinical features of KLICK syndrome associated with a specific POMP mutation." (PMID 32425927, 2020). "To date, ~20 cases of KLICK syndrome associated with the recurrent hotspot mutation in the 5′ UTR of POMP have been reported." (PMID 32425927, 2020). "In fact, a homozygous single-nucleotide deletion in the 5′ UTR of POMP causes KLICK syndrome, whereas heterozygous frameshift variants in the penultimate exon of POMP result in systemic autoinflammatory diseases." (PMID 32425927, 2020). "A human mutation in POMP is associated with KLICK syndrome, a skin disorder also characterized by hyperproliferation and thickening of palms and footpads." (PMID 29035697, 2017). "A one base pair deletion (−95C) in POMP is associated with keratosis linearis, ichthyosis congenital, and sclerosing keratoderma (KLICK syndrome) in several European families." (PMID 24490108, 2013). "We propose that KLICK syndrome associated with the POMP mutation be categorized as an AiKD." (PMID 32425927, 2020). "Thus, KLICK syndrome is caused by a reduction in POMP levels that leads to proteasome insufficiency in differentiating keratinocytes." (PMID 32425927, 2020). "It is considered that the disrupted proteasome assembly caused by the POMP mutation might lead to both skin inflammation and then hyperkeratosis in KLICK syndrome." (PMID 32425927, 2020). "We propose that KLICK syndrome caused by the specific 1-bp nucleotide deletion mutation in the regulatory region of POMP might be in a spectrum of proteasome-associated phenotypes." (PMID 32425927, 2020). "In KLICK syndrome, the disrupted proteasome assembly caused by the POMP mutation leads to hyperkeratosis and might also lead to autoinflammation by increased type 1 interferon signaling." (PMID 32425927, 2020). "All described patients with KLICK syndrome harbored the same homozygous 1-bp deletion in the 5′ UTR of the POMP gene." (PMID 32425927, 2020). "Investigation of skin biopsies from KLICK syndrome patients showed altered epidermal distribution of POMP, α4 (PSMA7), and β5 (PSMB5), when compared to controls." (PMID 24490108, 2013). "From our results we concluded that siRNA silencing of POMP models KLICK syndrome in vitro." (PMID 22235297, 2012).
colorectal cancer (3 papers, 2020 to 2021). A primary or metastatic malignant neoplasm that affects the colon or rectum. "Upregulation of the POMP-20S proteasome axis further results in poor prognosis of colorectal cancer patients." (PMID 34884489, 2021). "More importantly, upregulation of the axis promotes tumor growth and metastasis in vivo, and colorectal cancer patients with higher POMP/NRF3 expression levels exhibit lower overall and disease-free survival rates." (PMID 32123008, 2020). "In addition, we showed that higher POMP/NRF3 mRNA levels correlated significantly with lower overall survival and lower disease-free survival rates of these cancer patients, corroborating the importance of the NRF3-POMP axis for cancer development and colorectal cancer prognosis." (PMID 32123008, 2020).
breast carcinoma (2 papers, 2020 to 2021). "Intriguingly, high POMP expression is associated with poor prognosis in endoplasmic reticulum (ER) α-positive breast cancers, and POMP expression is mitigated by the tumor suppressor miR-101 in normal cells." (PMID 32962187, 2020). "In breast cancer, miR-101 has been reported to act as a suppressor of cell proliferation by decreasing the level of DNA methyltransferase 3A (DNMT3A) and targeting proteasome maturation protein (POMP) and Stathmin 1 (Stmn1)." (PMID 34272359, 2021).
multiple myeloma (2 papers, 2018 to 2021). "An association between overexpression of POMP and increased levels of NRF2 was also observed in bortezomib-resistant myeloma cells." (PMID 30405034, 2018). "Bortezomib-resistant myeloma cells overexpressed proteasome maturation protein (POMP)." (PMID 30405034, 2018).
acanthosis nigricans (1 paper, 2020). A melanotic cutaneous lesion that develops in the axilla and other body folds. "Although the detailed cutaneous features of PRAAS2 were lacking, this patient with POMP mutation presented with periorbital erythema, annular plaques, and acanthosis nigricans." (PMID 32425927, 2020).
asthma (1 paper, 2025). "The results identified MEblack as a cluster containing 741 asthma-related core genes, including POMP, GUSBL2, RBM39, PSMA6, RFX1, TCEB1, PSMD6, and others." (PMID 41403444, 2025). "Specifically, WGCNA highlighted the MEblack module (741 genes), enriched in proteostasis regulators (e.g., POMP, PSMA6) and immune signaling components, as a key driver of asthma pathogenesis." (PMID 41403444, 2025).
CANDLE syndrome (1 paper, 2016). "Recently, new mutations related to the CANDLE syndrome were identified in the PSMA3 gene coding α7, PSMB4 coding β7, and PSMB9 coding β1i as well as PSMB8 and proteasome maturation protein (POMP) genes from 8 patients." (PMID 29259686, 2016).
colorectal adenocarcinoma (1 paper, 2020). The most common type of colorectal carcinoma. "Here, we first confirmed the positive correlation between NRF3 expression and POMP expression in patients with colorectal adenocarcinoma (COAD) or rectal adenocarcinoma (READ)." (PMID 32123008, 2020).
erythrokeratoderma (1 paper, 2018). An umbrella term for a group of rare genetic skin disorders characterized by well-demarcated plaques of reddened, dry and thickened skin. "The remaining three patients had Netherton syndrome (one case due to SPINK5 mutations), erythrokeratoderma (one case due to GJB3 mutation), and KLICK (keratosis linearis with ichthyosis congenita and sclerosing keratoderma) syndrome (one case carrying POMP mutation)." (PMID 29618363, 2018).
keratinization disease (1 paper, 2023). "Since then, endotypes underlying novel entities matching the concept of autoinflammatory keratinization diseases have been discovered (mutations of JAK1, POMP, and EGFR)." (PMID 38103162, 2023).
rectal adenocarcinoma (1 paper, 2020). "More importantly, the NRF3-POMP axis supports tumorigenesis and metastasis, with higher NRF3/POMP expression levels correlating with poor prognoses in patients with colorectal or rectal adenocarcinoma." (PMID 32123008, 2020).
cancer (10 papers, 2020 to 2025). A tumor composed of atypical neoplastic, often pleomorphic cells that invade other tissues. "Inhibition of POMP can result in the accumulation of cyclin-dependent kinase inhibitors and thus hamper cancer cell proliferation in vitro and in vivo." (PMID 37342762, 2023). "This review first introduces that NRF3 promotes cancer development through proteasome regulation, by inducing the gene regulation of proteasome maturation protein (POMP) and cytoplasmic polyadenylation element-binding protein 3 (CPEB3)." (PMID 34884489, 2021). "NRF3, which is highly expressed in various cancers, enhances 20S proteasomal assembly by inducing the expression of the 20S proteasome maturation protein POMP." (PMID 34356615, 2021). "Therefore, NRF1 maintains a 26S proteasome activity for normal development, whereas NRF3 alternatively maintains 20S proteasome activity for cancer development through both POMP-20S proteasome and CPEB3-NRF1 axes." (PMID 34884489, 2021). "Actually, POMP expression levels are increased in several cancer types." (PMID 32123008, 2020). "The selected cancers KIRC, LAML, LGG, LIHC, and LUAD were now classified based on changes in 14 proteasomal subunits and the proteasome maturation protein POMP using ingenuity pathway analysis (IPA)." (PMID 40862469, 2025). "In cancer cells, NRF3 upregulates the assembly of the 20S proteasome by directly inducing the gene expression of the 20S proteasome maturation protein POMP." (PMID 32123008, 2020). "In cancer cells, NRF3 induces POMP gene expression and enhances 20S proteasome assembly." (PMID 32123008, 2020). "This suggests that NRF3 positively regulates the assembly of 20S proteasomes in cancer cells by inducing the gene expression of its assembly chaperone POMP but not of the 20S proteasome subunits." (PMID 32123008, 2020).
tumor (5 papers, 2019 to 2024). "Mouse xenograft experiments revealed that NRF3 overexpression results in increased tumor volume and weight, while the POMP-ARE mutation inhibited this effect." (PMID 32123008, 2020). "Furthermore, xenograft and hepatic metastatic mouse models showed that NRF3 increases tumorigenesis and metastasis, whereas POMP-ARE mutation inhibits this tumor burden." (PMID 34884489, 2021). "This suggests that NRF3 promotes tumor growth by enhancing 20S proteasome assembly through direct binding to the ARE of the POMP gene, promoting the upregulation of its expression." (PMID 32123008, 2020). "Moreover, it has been reported that miR-101 targets the proteasome assembly factor POMP and suppresses tumor cell proliferation." (PMID 30718521, 2019). "NRF3 induces the gene expression of POMP for 20S proteasome assembly and CPEB3 for NRF1 translational repression, inhibiting tumor suppression responses, including cell-cycle arrest and apoptosis, with resistance to a proteasome inhibitor anticancer agent bortezomib." (PMID 34884489, 2021).
infection (3 papers, 2020 to 2025). The state of being infected such as from the introduction of a foreign agent such as serum, vaccine, antigenic substance or organism. "The role of POMP in the infection process of Aedes aegypti by DENV2 requires further investigation." (PMID 39861856, 2025).
genodermatosis (1 paper, 2012). "Taken together, we show that the POMP 5′ UTR mutation associated with KLICK genodermatosis results in reduced POMP expression, which in turn causes reduced levels of proteasome subunits and filaggrin as well as increased ER stress." (PMID 22235297, 2012). "In this study we present additional evidence for an association between decreased amounts of POMP, increased ER stress and KLICK genodermatosis." (PMID 22235297, 2012).
POMP also shares sentences with these, for which no sentence is quoted: Erythema (1 paper); exfoliation glaucoma (1); Hyperkeratosis (1); ichthyosis congenita (1); Netherton syndrome (1); Obesity (1); primary angle-closure glaucoma (1); prostate carcinoma (1); skin disorder (1).